TNF (tumor necrosis factor)
Diseases named in the same sentence as TNF in open-access papers (continued):
Sharing a sentence is not in itself a finding about the gene and the disease.
Encephalopathy (54 papers, 2007 to 2025). Encephalopathy is a term that means brain disease, damage, or malfunction. "In fact, by acting through TNF receptor 1 (TNFR1), TNFα in the brain can significantly influence the development of sepsis associated encephalopathy (SAE) and mediate certain NG functions." (PMID 40534875, 2025). "Although microglia have protective activity, hyperactivated microglia release high levels of inflammatory cytokines such as IL-6, IL-1β, and TNF-α, leading to neuronal death and chronic inflammation, which is the degenerative main cause of encephalopathy." (PMID 36176437, 2022). "Previous studies reported increased serum and cerebrospinal fluid concentrations of IL-1β, IL-6, IL-10, and TNF-α, as well as increased transcription of their coding genes in patients with influenza-associated encephalopathy and FS." (PMID 34300253, 2021). "In particular, increased IL-6 and TNFα is linked to a poor prognosis in infants suffering encephalopathy, these factors known to stimulate extrinsic pathways of cell death." (PMID 23454862, 2013). "CM, a clinically complex syndrome of coma and potentially reversible encephalopathy, is associated with increased levels of proinflammatory cytokines like tumor necrosis factor (TNF)-α, interferon (IFN)-γ and lymphotoxin, and increasingly recognized long-term sequelae in survivors." (PMID 17997848, 2007). "In our survey, three HA20 patients with encephalopathy who were started on mycophenolate mofetil or anti-TNF-α agents after being treated with corticosteroids for CNS involvement have shown no relapse of neurological disease to date." (PMID 40574834, 2025). "The findings suggested that inflammatory factors, such as IL‐1β, IL‐18 and TNF‐α, play an important role in the pathogenesis of encephalopathies." (PMID 38683122, 2024). "For instance, patients with encephalopathies due to acute liver injuries showed a significant decrease in pro-inflammatory cytokines (e.g., tumor necrosis factor (TNF) and interleukin (IL)-1β and IL-6) upon exposure to cold." (PMID 37332670, 2023). "Fourth, a patient with norovirus-associated encephalopathy showed elevated concentrations of cerebrospinal fluid interleukin-6, interleukin-10, interferon-γ, and tumor necrosis factor-α suggesting that her encephalopathy was related to hypercytokinemia." (PMID 37477790, 2023). "Indeed, TNF-α is a key mediator of septic encephalopathy, as TNF-α-deficient mice are resistant to LPS-induced encephalopathy and TNF-α might activate the TNF-related apoptosis-inducing ligand (TRAIL) receptor leading to cell apoptosis on neurons, astrocytes, and oligodendrocytes." (PMID 35628259, 2022). "Attention is drawn to the curious phenomenon of the same encephalopathies being often defined only in TNF or IL‐1β terms." (PMID 35174650, 2022). "IL-17, IL-6, IL-21, IL-22, IL-23, and TNF-α are inflammatory cytokines generated by Th17 cells, of which IL-17A is the most important cytokine in Th17-mediated encephalopathy." (PMID 36176437, 2022). "IL-6 and TNFα are the signature cytokines of lung inflammation and have been associated with severe RSV diseases such as severe bronchiolitis and encephalopathy." (PMID 34929018, 2021). "Our study provides new insights into GAS-induced central nervous system inflammation, such as encephalopathy, which can be attenuated by circulating TNF blockage." (PMID 30837977, 2019). "RSV-induced encephalopathy is accompanied by neuronal cell damage and frequently altered expression levels of pro-inflammatory cytokines, such as IL-6, IL-8 and TNF-α." (PMID 29427996, 2018). "Inflammatory cytokines such as IL-6 and TNF-α are involved in the pathology of encephalopathy characterized by cytokine storm." (PMID 29725488, 2018). "It is shown that the over-expression of TNF-α in transgenic mice consistently results in severe inflammation, encephalopathy, and neurodegeneration." (PMID 29296174, 2017).
Encephalopathy (continued). "During the acute stage of encephalopathy serum and cerebrospinal fluid concentrations of inflammatory cytokines such as tumor necrosis factor alpha (TNF-alpha), interleukin-1 (IL-1), and interleukin-6 (IL-6) become elevated." (PMID 28453565, 2017). "The systemic administration of Ig following HI encephalopathy significantly reduced the TNF-α, IL-6 and IL-1β mRNA expression levels in the ischemic tissue in the Ig + hypoxia group compared with those in the hypoxia group." (PMID 24520277, 2014). "Rather, inflammation, and especially TNF levels seem to correlate with disease severity, encephalopathy, and death." (PMID 21772838, 2012). "Elevated levels of TNF are also seen in the cerebral spinal fluid (CSF) of infected children and correlated with encephalopathy." (PMID 21772838, 2012). "CM is an acute – and potentially reversible – encephalopathy with increased serum-levels of pro-inflammatory cytokines such as tumor necrosis factor (TNF), interferon-γ (IFN-γ), and lymphotoxin (LT)." (PMID 18179698, 2008). "JEV induces encephalopathy by activating microglial cells and astrocytes that can increase the levels of proinflammatory cytokines such as tumor necrosis factor alpha (TNF-α), interleukins (IL-6, IL-8 and IL-10), and RANTES (regulated on activation, normal T-cell expressed and secreted)." (PMID 37946006, 2024). "Key pro-inflammatory cytokines such as IL-1 beta and TNF-α could develop encephalopathy by stimulating brain edema, astrocytosis, neutrophil infiltration, and apoptosis." (PMID 38254870, 2024). "In our case, high levels of serum IL-6 and TNF-α were considered to be the cause of the encephalopathy; regrettably however, the blood flow was not examined." (PMID 31922014, 2018). "Importantly, systemic TNF-α has been shown to activate cerebral microglia in infection-induced encephalopathy and murine neurocysticercosis, and subsequently up-regulates other inflammatory mediators and neurotransmitters." (PMID 24932221, 2014). "IL-6 and TNF-α levels in the RSV-infected group were substantially elevated compared with that in the uninfected control group as the duration of RSV infection extended (P < 0.01), suggesting that encephalopathy-associated pro-inflammatory molecules are induced by RSV infection in N2a cells." (PMID 29427996, 2018). "Key laboratory findings included significantly lower levels of interferon-gamma (IFN-γ) (P < .001), tumor necrosis factor-alpha (TNF-α) (P < .001), and a decreased CD4+/CD8 + ratio (P = .001) compared to the non-encephalopathy group." (PMID 41189156, 2025). "The mRNA expression of TNF-α and its receptor, TNFR1 is also upregulated following LPS induction in the septic encephalopathy model." (PMID 36435787, 2022). "Regarding brain damage, BAM15 attenuated encephalopathy score (SHIRPA) and several injury parameters, including brain cytokine (TNF-α), apoptosis (activated caspase 3), blood–brain barrier defect (Evan’s blue dye assay), s100β, and miR370-3p." (PMID 35628259, 2022). "Both TNF-α and ADMA were increased in plasma and the brain in encephalopathy induced by acute or chronic liver failure." (PMID 27445694, 2016). "The levels of tumor necrosis factor-alpha (TNF-α) and asymmetric dimethylarginine (ADMA) are both increased in plasma and brain in encephalopathy induced by chronic liver failure." (PMID 27445694, 2016). "It has also been shown that TNF-α level in ALF correlated subsequent serious clinical complications, such as infection and encephalopathy." (PMID 26516376, 2015). "We also showed that CSF IL-6 and TNF-α levels were elevated only in the HHV-6 encephalopathy group, but not in the HHV-6 complex FS group." (PMID 25294958, 2014). "Plasma TNF-α levels were significantly increased 9 h after AOM injection (12.7-fold; p<0.001) and remained at similar levels 12 h after AOM injection and at coma stages of encephalopathy." (PMID 23166746, 2012).
Encephalopathy (continued). "In addition to increases of TNF-α, significant increases in plasma IL-6 (732.5-fold; p<0.001) and CD40L (8.3-fold; p<0.001) were observed in AOM-treated mice at coma stages of encephalopathy." (PMID 23166746, 2012). "This group displayed markedly lower levels of IFN-γ (P < .001), TNF-α (P < .001), and a decreased CD4+/CD8+ ratio (P = .001) compared to the no encephalopathy group." (PMID 41189156, 2025). "In this case, the patient had raised levels of TNF-alpha, low lymphocyte count and a raised CRP in the absence of any cerebrospinal fluid evidence of virus or MRI and EEG evidence of an encephalopathy." (PMID 32696735, 2020).
glomerulonephritis (54 papers, 2010 to 2025). A renal disorder characterized by damage in the glomeruli. "ICAM‐1 expression is stimulated and increased by oxidative stress and TNF‐α and is associated with disease progression in several types of human and experimental glomerulonephritis." (PMID 32822114, 2020). "Anti-TNF-ɑ treatments or TNF-deficient mice are partially protected against glomerular injury through lower renal infiltration of T cells and neutrophils in experimental models of glomerulonephritis." (PMID 29340080, 2017). "TNF-α plays a pivotal role in the development and progression of different forms of glomerulonephritis." (PMID 38765394, 2024). "Renal involvement and central nervous system symptoms are rare in both types, but severe clinical presentations such as glomerulonephritis can occur in anti-TNFα inhibitor-induced DIL." (PMID 39618753, 2024). "TNF-α blockade reduced proteinuria, inflammation status, and renal scaring in mice and rat models of glomerulonephritis." (PMID 35328704, 2022). "TNF is involved in the pathogenesis of many kidney diseases, including ischaemic kidney injury, renal graft rejection, and glomerulonephritis, which is often part of systemic vasculitis." (PMID 36534664, 2022). "As it is known that glomerular visceral epithelial cells can produce TNFα, the interaction between TNFα and anti TNFα antibodies (produced as a consequence of infliximab therapy) can result in glomerulonephritis and membranous nephropathy." (PMID 31820145, 2021). "Anecdotal observations and case reports suggest clinical benefits from using anti TNFα in the treatment of glomerulonephritis in IBD patients." (PMID 31820145, 2021). "Glomerulonephritis: Very few cases of glomerulonephritis were reported with TNF-α inhibitors; discontinuation of these agents with steroids and immunosuppressive medications leads to improvement." (PMID 33209528, 2020). "Plasmin also reportedly inhibits TNF‐α‐induced apoptosis in monocytes, regulates the clearance of dead cells, and plays a role in the pathogenesis of glomerulonephritis." (PMID 32237065, 2020). "Numerous in vivo and in vitro studies have shown that exposure of glomerular cells to TNF-α induces glomerular dysfunctions similar to those observed in glomerulonephritis." (PMID 29724888, 2018). "Renal expression of TNF is up-regulated in experimental animals and patients with glomerulonephritis (GN)." (PMID 23869211, 2013). "Moreover, there are reports that TNF inhibitor therapy can lead to nephrotoxicity, manifesting as glomerulonephritis and AKI." (PMID 39830664, 2024). "The anti-TNF-α produced by glomerular epithelial cells in patients with glomerulonephritis can lead to abnormal mucosal immune responses, such as the deposition of immune complexes of the drug itself or anti-drug antibodies, which can induce cell apoptosis and impair kidney function." (PMID 39421866, 2024). "Interestingly, glomerular visceral epithelial cells can also produce TNF-α, which plays a significant role in an aberrant mucosal immune response leading to glomerulonephritis." (PMID 38628140, 2024). "Since HPSE1 is also involved in inflammation, the increased HPSE1 and TNF-α expression might be prevented if HPSE2 is administered concomitant with LPS at induction of experimental glomerulonephritis." (PMID 37180718, 2023). "Moreover, cortical HPSE1 and TNF-α mRNA expression were unaltered like in the LPS-induced glomerulonephritis model." (PMID 37180718, 2023). "Similar to previous studies which showed that silica induces glomerulonephritis, administration of myrrh with or without prednisolone to rats improved renal histopathology, and kidney function, and reduced TNFα with time compared with silica treated group." (PMID 35930173, 2022). "TNFα producing macrophages are involved in the pathology of glomerulonephritis." (PMID 35095868, 2021).
glomerulonephritis (continued). "Acute anti-thy1 glomerulonephritis in the rat is characterized by an injury phase (6–48 h after induction) with mesangial cell lysis, macrophage influx, and overexpression of proinflammatory cytokines such as TNF-α and IL-1." (PMID 27243813, 2016). "JNK blockade in an experimental model of anti-GBM glomerulonephritis attenuated both glomerular and tubulointerstitial damage with the effect being mediated by a reduction in the release of pro-inflammatory mediators such as TNF-alpha from macrophages." (PMID 26415098, 2015). "In the present study, we evaluated the participation of immunoglobulins, T cells, adhesion molecules, and proliferation and apoptosis and related cytokines TNF-α and IL-1α in the renal lesions in dogs with naturally acquired VL to better understand the immunopathogenesis of glomerulonephritis in VL." (PMID 20459816, 2010). "Immunohistochemistry analysis showed that TNF-α, IL-6 and IL-10 were mainly expressed by mesangial cells and infiltrating macrophages in the glomeruli, as well as in the tubulointerstitial area and endothelium during the course of tubulointerstitial and glomerular nephritis in ECM." (PMID 38787228, 2024). "This study investigates the therapeutic potential of blocking key CD4+ Th1 effector cytokines, TNF-α and IFN-γ, in experimental anti-myeloperoxidase (MPO) glomerulonephritis (GN)." (PMID 40735321, 2025). "Remarkably, both HPSE2 protein and peptides improved kidney function in LPS-induced glomerulonephritis, while HPSE1 and TNF-α mRNA expression levels remained unaltered." (PMID 37180718, 2023). "Findings from KEGG enrichment pathway analysis and bubble plots revealed that glomerulonephritis targets were mainly enriched in AGE-RAGE, HIF-1, IL-17, and TNF signaling pathways in diabetic complications." (PMID 36998608, 2023). "Small molecule MIF antagonists also resulted in reduced glomerulonephritis and interstitial inflammation, lower levels of CD74+ and CXCR4+ leukocyte recruitment and decreased circulating TNF-α." (PMID 30787934, 2019). "These accumulating macrophages secrete inflammatory cytokines and chemokines, including IL23, TNF-α and COX-2 that contribute to the apoptosis of tubular epithelial cells and drive glomerulonephritis." (PMID 26208003, 2015). "Intrinsic kidney cells are the predominant cellular source of TNF, leading to inflammatory damage in glomerulonephritis, while invading leukocytes do not contribute." (PMID 38765394, 2024). "To address whether TNF-α affects expression of FLASH in rat glomerulonephritis, we monitored expression of FLASH protein in mouse MCs treated with TNF-α." (PMID 26208142, 2015). "Real-time PCR analysis of whole kidneys identified a marked increase in the gene expression of leukocyte markers (CD68, CD3e), proinflammatory cytokines (TNF-α, IFN-γ, CCL2) and macrophage elastase (MMP-12) in untreated and vehicle-treated mice at day 15 of glomerulonephritis." (PMID 26700873, 2015). "Importantly, systemic concentrations of TNF-α and IL-6 correlate with SLE disease activity in humans and treatment with exogenous IL-6 exacerbates glomerulonephritis in NZBWF1 mice." (PMID 25978333, 2015). "TNF-α concentrations are elevated in both sera and renal tissue of lupus-prone mice and SLE patients alike and its levels correlate with disease activity and glomerulonephritis." (PMID 24945254, 2014). "When cells expressing TNF-α were quantified, fewer cells were detected in samples of VL dogs presenting different patterns of glomerulonephritis than in the non-infected control animals (p < 0.05, (Kruskal Wallis and Dunn's tests)." (PMID 20459816, 2010). "Notably, the TNF-α mRNA expression level in the renal cortex did not significantly increase in mice with LPS-induced glomerulonephritis, and was not further affected by any of the treatments." (PMID 37475889, 2023).
glomerulonephritis (continued). "In contrast to TNF-α, IL-6 mRNA expression levels were near-significantly decreased by addition of HPSE2 in experimental glomerulonephritis but not in DN." (PMID 37180718, 2023).